LRP5 (LDL receptor related protein 5)
Diseases named in the same sentence as LRP5 in open-access papers (continued):
Sharing a sentence is not in itself a finding about the gene and the disease.
osteosarcoma (17 papers, 2009 to 2024). A usually aggressive malignant bone-forming mesenchymal neoplasm, predominantly affecting adolescents and young adults. "For example, osteosarcoma tumors overexpressing LRP5, a Wnt co-receptor, and nuclear β-catenin are associated with a poorer prognosis and decreased patient survival." (PMID 37176108, 2023). "A series of studies have documented the associations of LRP5 with several types of human malignancies, including osteosarcoma, leukaemia, prostate, parathyroid, breast and gastric cancers." (PMID 34997691, 2022). "In osteosarcoma, LRP5 expression has also been reported to be associated with decreased event-free survival." (PMID 34885123, 2021). "To confirm the potential impact of novel or very rare exonic variants in LRP5 in bone, we performed site‐directed mutagenesis in SaoS2 human osteosarcoma cell lines." (PMID 30283887, 2018). "Additionally, the expression of LRP-5, which is a coreceptor for Wnt, is associated with metastasis of osteosarcoma cells." (PMID 34671398, 2021). "LRP5, as a co-receptor for the Wnt pathway, has been shown to correlate significatively with metastasis and overall survival in osteosarcoma." (PMID 37628576, 2023). "Based on the discovery of Wnt ligands, LRP5/6 co-receptors, or cytoplasmic β-catenin staining, some investigators claimed that osteosarcoma samples had aberrant Wnt/β-catenin activation mediated by an autocrine mechanism." (PMID 37176108, 2023). "LRP5 was frequently expressed in osteosarcoma, and correlated significantly with the chondroblastic subtype of osteosarcoma and metastasis." (PMID 34130697, 2021). "It has also been reported that dominant-negative LRP5 can inhibit the proliferation and metastasis of osteosarcoma cells via downregulating N-cadherin, MMPs, Twist, Slug, and Snail." (PMID 34671398, 2021). "Studies have identified genes which specifically suppress in vitro migration and invasion of osteosarcomas, including LRP5 and IGFBP5." (PMID 23767896, 2013). "Numerous studies have demonstrated an involvement of the Wnt pathway, including thorough expression of LRP5 as involved in osteosarcoma disease progression." (PMID 23125530, 2012). "Likewise, another in vivo study also found that dominant negative LRP5 impeded the osteosarcoma tumorigenic potential and metastasis." (PMID 34130697, 2021). "More specifically, previous studies have shown that downregulating the Wnt pathway by transfecting Dkk-3 and dominant-negative LRP5 into osteosarcoma cells significantly reduced invasion capacity and cell motility potentially by recruiting β-catenin to the cell surface to promote cell-cell adhesion." (PMID 23125530, 2012). "When osteosarcoma cells are transfected with dominant negative, soluble LRP5 (sLRP5), epithelial–mesenchymal transition (EMT) is reversed, suggesting wildtype LRP5′s role in promoting EMT and metastasis." (PMID 31382613, 2019). "Inhibition of Wnt signaling by overexpression of secreted Wnt antagonists soluble LRP5, Frzb, and WIF1 markedly down-regulated mRNA and protein expression of NRP2 in osteosarcoma cell lines." (PMID 25890345, 2015). "LRP5 was found to be overexpressed and correlated with tumor metastasis in high-grade osteosarcoma; blocking the LRP5 by its dominant negative form decreased tumorigenicity and metastasis of osteosarcoma." (PMID 22570728, 2012). "For instance, LRP5 is overexpressed in high‐grade osteosarcoma, and inhibiting the canonical Wnt/β‐catenin pathway by using a soluble dominant‐negative LRP5 could suppress the invasive capacity and epithelial to mesenchymal transition (EMT) in osteosarcoma cells." (PMID 34997691, 2022).
prostate carcinoma (16 papers, 2008 to 2025). A carcinoma that arises from epithelial cells of the prostate gland. "LRP5/6 are infrequently mutated in primary (≤0.61%) and metastatic (≤2.1%) prostate cancer, and are predominantly missense variants." (PMID 35204808, 2022). "In the previous studies reports, the low-density LRP5 regulates the osteoblastic metastases and the tumor caused new bone formation in prostate cancer." (PMID 29108281, 2017). "Our study revealed that circSPIRE1, regulated by hnRNPA1’s SDMA-mediated post-translational modifications, undergoes rolling circle translation to encode rtSPIRE1, which promotes prostate cancer progression by stabilizing LRP5 and activating the PI3K/AKT signaling pathway." (PMID 40713830, 2025). "To confirm that LRP5 is a critical mediator of the pro-tumorigenic effects of rtSPIRE1 in prostate cancer, we conducted a series of rescue experiments." (PMID 40713830, 2025). "In prostate cancer, rtSPIRE1 stabilizes LRP5 and activates the PI3K/AKT signaling pathway to enhance cell proliferation and migration." (PMID 40940800, 2025). "Our findings demonstrated that rtSPIRE1 enhances oncogenic signaling in prostate cancer by stabilizing LRP5, activating the PI3K/AKT pathway and promoting cancer progression." (PMID 40713830, 2025). "LRP5 expression upregulation has been observed in various cancer types, including gastric cancer, prostate cancer, and osteosarcoma." (PMID 40940800, 2025). "Together, these findings reveal that rtSPIRE1 critically regulates LRP5 stability and function, establishing a key mechanism through which rtSPIRE1 facilitates tumor growth and metastasis in prostate cancer." (PMID 40713830, 2025). "In our study, we demonstrated that rtSPIRE1 reduces ubiquitin-mediated proteasomal degradation of LRP5, resulting in LRP5 upregulation within prostate cancer cells." (PMID 40713830, 2025). "Upstream factors of the Wnt pathway, such as Wnt ligands, Frizzled receptors, LRP5/6 co-receptors, exhibit specific alterations in expression within prostate cancer tissues, correlated with tumor differentiation, invasiveness, and prognosis." (PMID 38994113, 2024). "Analogously, silencing of LRP5 in prostate cancer cells leads to a robust decrease in invasion growth and skeletal metastasis in vitro and in vivo by decreasing the expression of pro‐invasive and pro‐metastatic genes." (PMID 34997691, 2022). "In relation to cancer progression, LRP5 has been shown to be involved in mediating Wnt/β-catenin signaling in skeletal metastasis prostate cancer (PC) due to the increased level of Wnt-1 and β-catenin proteins in both PC cell lines and primary specimens." (PMID 31031810, 2019). "Genes encoding FZD2-5, FZD8, VANGL1, ROR1, RYK, LGR4, LRP5 and 6, and GPC4 were highly expressed in at least three prostate cancer cell lines." (PMID 29717114, 2018). "Importantly, LRP5 knockdown attenuates rtSPIRE1-induced proliferation and invasion in prostate cancer, underscoring the pivotal role of the rtSPIRE1-LRP5 interaction in cancer progression." (PMID 40713830, 2025). "Together, these findings indicate additional work is needed to establish how LRP5/6 genetic alterations contribute to prostate cancer growth, to gain new insight into how these Wnt co-receptors function, and to discover new therapeutic opportunities to treat this lethal disease." (PMID 35204808, 2022). "LRP5 has also been shown to mediate the prostate cancer-induced formation of new bone in an ex vivo bone formation assay, indicating LRP5 may contribute to the formation of prostate cancer skeletal metastases." (PMID 35204808, 2022). "Mechanistically, rtSPIRE1 stabilized LRP5 by inhibiting its ubiquitination and degradation, leading to sustained activation of the PI3K/AKT signaling pathway, which ultimately promotes prostate cancer cell proliferation and migration." (PMID 40713830, 2025). "By stabilizing LRP5, rtSPIRE1 activates the PI3K/AKT signaling pathway, thereby promoting prostate cancer progression." (PMID 40713830, 2025).
prostate carcinoma (continued). "LRP5 and LRP6 amplification is observed in up to 7.2% and 2.7% of metastatic prostate cancers, yet are relatively infrequent in primary prostate cancer (0–2.1%)." (PMID 35204808, 2022). "For example, the activation of Wnt receptors FZD8 and LRP5 was reported to facilitate cell migration and invasion by accelerating EMT in prostate cancer." (PMID 34568020, 2021). "Mesd, a specialized chaperone that binds to LRP5/6 on the cell surface, inhibits LRP5/6 ligands and suppresses downstream WNT/β-catenin signaling in prostate cancer." (PMID 31382613, 2019). "Interestingly, treatment with recombinant MESD protein, a LRP5/6 chaperone protein able to bind to mature LRP5 and LRP6 on the cell surface, decreases LRP6 phosphorylation in prostate cancer cells, inhibiting their proliferation and tumorigenic potential." (PMID 31412666, 2019). "In support, LRP5 knockdown in PC-3 cells reduced tumor burden and skeletal metastasis in xenografts, and small molecule inhibitors that reduce LRP6 expression and phosphorylation (e.g., niclosamide, salinomycin, and silibinin) can inhibit prostate cancer cell growth and increase apoptosis." (PMID 35204808, 2022). "Furthermore, CM from Lrp5-overexpressing but not parental osteocytes reduced the proliferative and invasive properties of PC-3 prostate cancer cells." (PMID 34230453, 2021). "Previous studies showed that LRP6 was important for efficient intoxication of human M2182 prostate carcinoma cells but other studies performed with cells from gene-knockout mice demonstrated no role for either LRP6 or the related LRP5 protein in anthrax toxin entry." (PMID 18350154, 2008). "Notably, doxycycline-inducible expression of DKK3 in LNCaP prostate cancer cells reduced cell proliferation but did not alter β-catenin cytoplasmic levels or inhibit Wnt/β-catenin signaling, consistent with the fact that DKK3 does not bind to the Wnt co-receptors LRP5/6 or KREMEN." (PMID 35204808, 2022).
atherosclerosis (14 papers, 2015 to 2025). A disease characterized by the build-up of fatty material and calcium deposition in the arterial wall resulting in partial or complete occlusion of the arterial lumen. "To determine if other receptors were causing the lipid infiltration observed in aortas of Lrp5−/− mice, we analysed gene expression of receptors described to be involved in the initial stages of atherosclerosis lesions." (PMID 25656427, 2015). "We hypothesized that LRP5 and the Wnt signalling pathway have a role in the inflammatory process associated to atherosclerosis progression." (PMID 25656427, 2015). "LRP5 variants have been linked to coronary artery disease (CAD), atherosclerosis, and insulin resistance." (PMID 40940800, 2025). "In atherosclerosis, targeted inhibition of LRP5 in plaque-resident macrophages alters lipid uptake and presents a novel therapeutic avenue to mitigate lesion progression while potentially preserving its systemic metabolic benefits." (PMID 40940800, 2025). "Recently, much attention has been paid to the interaction between PCSK9 and LRP5/6 in the development and progression of atherosclerosis." (PMID 36970356, 2023). "Lastly, Lrp5 is also important for macrophage phagocytosis and clearance of lipids (e.g., low density lipoproteins), as Lrp5−/− mice are prone to development of atherosclerosis when fed a high fat diet." (PMID 31417574, 2019). "We have shown that LRP5 is involved in several cellular processes including inflammation, monocyte differentiation, dislypidemia and atherosclerosis progression." (PMID 31220102, 2019). "Although it plays a protective role in acute injuries such as myocardial infarction and acute kidney injury, LRP5 also contributes to chronic pathologies such as tubulointerstitial fibrosis, polycystic kidney disease, and atherosclerosis through fibrotic and inflammatory pathways." (PMID 40940800, 2025). "The paradoxical role of LRP5 in atherosclerosis warrants further investigation." (PMID 40940800, 2025). "Accordingly, LRP5 knockout mice develop atherosclerosis with a high fat diet." (PMID 33969358, 2021). "Therefore, a systematic blockade of monocyte/macrophage infiltration in the prevention of atherosclerosis may be less effective than originally expected if the levels of macrophage‐derived LRP5+MV are affected and reduced." (PMID 34288375, 2021). "LRP5 and LRP6, as coreceptors of PCSK9, promote atherosclerosis by activating the Wnt/β-catenin signaling pathway, resulting in significant proliferation of VSMCs and decreased anti-inflammatory macrophages." (PMID 36970356, 2023). "The Wnt coreceptor Lrp5 has been shown to play an important for macrophage phagocytosis and clearance of LDL as shown in Lrp5−/− mice, which develop atherosclerosis on a high fat diet." (PMID 33969358, 2021). "There is ongoing controversy on the role of LRP5 and the canonical Wnt/β-CATENIN pathway in lipid induced vascular damage and atherosclerosis." (PMID 25656427, 2015). "However, total cholesterol levels in HC Lrp5−/− mice that had a significantly higher aortic lipid infiltration were higher than those in HC Wt mice, suggesting an involvement for LRP5 during dyslipidaemia, at the initial stages of atherosclerosis development." (PMID 25656427, 2015). "However, the contribution of LRP5 to atherosclerosis is still not well defined and its function may depend on cell lineage." (PMID 27680891, 2017).
osteopetrosis (13 papers, 2010 to 2024). Osteopetrosis, also known as marble bone disease, is a descriptive term that refers to a group of rare, heritable disorders of the skeleton characterized by increased bone density on radiographs. "Subsequently, gain-of-function mutations of the LRP5 have been shown to be associated with disorders of increased bone mass, such as Van Buchem's disease, osteopetrosis, and endosteal hyperostosis." (PMID 20843343, 2010). "Whereas, gain of function mutations of LRP5 have been shown to lead to disorders of increased bone mass such as sclerostosis, Van Buchem's disease, osteopetrosis and endosteal hyperostosis." (PMID 20843343, 2010). "However, recently some studies have revealed that LRP5 deficiency leads to increased osteoclast activity and bone loss, which is quite different from the manifestation of osteopetrosis." (PMID 37373559, 2023). "Traditionally, osteopetrosis has been thought to derive from enhanced osteoblast activity due to LRP5 affinity." (PMID 37373559, 2023). "It was proposed that this variation be eliminated from the osteopetrosis family of diseases after it was shown that the “increase in bone density in ADO I patients was caused by an osteoblastic defect, a mutation in low-density lipoprotein receptor-related protein 5 (LRP5)”." (PMID 36826034, 2023). "IKBKG, LRP5, and TNFSF11 are mainly due to the interaction of osteoblasts and osteoclasts, which cause an imbalance between bone formation and bone absorption, resulting in osteopetrosis." (PMID 37373559, 2023).
Norrie disease (12 papers, 2009 to 2025). A rare X-linked genetic vitreoretinal condition characterized by abnormal retinal development with congenital blindness. "Mouse models with genetic deficiency of Norrin or LRP5 exhibit disrupted Wnt signaling resulting in similar retinal vascular abnormalities as seen in human Norrie disease and FEVR." (PMID 37887287, 2023). "Norrie disease is associated with loss-of-function mutations in Norrin (NDP) (>100 mutations reported) whereas FEVR is caused by mutations in multiple genes including NDP/FZD4/LRP5/TSPAN12/ZNF408 and recently reported CTNNA1 and KIF11." (PMID 37887287, 2023). "The genes mutated in these diseases include NDP (norrin) in Norrie disease and FZD4, LRP5, and TSPAN12 in FEVR." (PMID 41086024, 2025). "The cause of inadequate norrin signalling in FEVR and Norrie disease is a primary deficiency due to a genetic mutation in the norrin- > FZD4, LRP5/6, TSPAN12 signalling pathway, affecting retinal vascular development beginning in utero." (PMID 35651932, 2022).
Obesity (10 papers, 2010 to 2025). Accumulation of substantial excess body fat. "A study of a Chinese rural population showed that low‐density lipoprotein receptor‐related protein 5 (LRP5) polymorphisms also interacted with obesity in T2DM, and LRP5 polymorphisms are associated with beta‐cell function and lipid metabolism." (PMID 38599825, 2024). "Loss of LRP5 together with Wnt proteins is responsible for the progression of obesity, NIDDM, and insulin resistance." (PMID 30678306, 2019). "Natural variants of LRP5 have been shown to be associated with obesity while the missense mutations of LRP6 are associated with the risk of bone loss, early coronary disease and metabolic syndrome." (PMID 31382613, 2019). "On the other hand, variants at the LRP-5 gene are strongly associated with obesity and LRP-5 knock-out mice showed increased plasma cholesterol and impaired glucose tolerance." (PMID 25140176, 2014). "Body weight is an important predictor of BMD, and BMI and obesity have been shown in a family-based analysis to be associated with LRP5 polymorphisms, underlining the role of LRP5 also in weight regulation." (PMID 20961463, 2010). "A previous study indicated that intronic variants of the LRP5 gene may be associated with obesity due to their impact on the WNT signaling pathway or lipid metabolism." (PMID 40625359, 2025). "Studies have shown that polymorphism of the LRP5 gene is associated with an increased LDL-C level, increased BMI, and obesity and presents a linkage imbalance." (PMID 32405501, 2020). "LRP5 encodes a co-receptor of WNT ligands and the polymorphisms are associated with T1D and obesity." (PMID 31382613, 2019). "The derived allele frequency of rs560826688 is 0.031, and belongs to LRP5 involved in hypertension, and derived allele frequency of rs563254260 is 0.026 and lies in SERPINF1 which relates to obesity and hypertension." (PMID 29420653, 2018).
gastric cancer (9 papers, 2019 to 2026). A primary or metastatic malignant neoplasm involving the stomach. "In gastric cancer, researchers have targeted LRP5 using the CRISPR/Cas9 knockout system, which led to a reduction in the proliferation of cancer cells in vitro and in vivo via cell cycle-associated gene inhibition." (PMID 40940800, 2025). "DKK1, a secretory antagonist that interacts with the Wnt coreceptor LRP5/6, thereby reducing cellular sensitivity to canonical Wnt ligands, has been identified as a factor that can enhance the recurrence of gastric cancer." (PMID 40296906, 2025). "In gastric cancer cells, HSP90b1 interacts with the client protein LRP5 and inhibits the ubiquitin–proteasome degradation pathway of LRP5, thereby influencing the progression of gastric cancer." (PMID 39048939, 2024). "LRP5 is highly expressed; its high expression suggests late clinical stage and poor prognosis of patients with gastric cancer." (PMID 38952556, 2024). "Salinomycin, an inhibitor of LRP5/6, inhibits the growth of GC by inhibiting Wnt signaling in CSCs, and salinomycin targeting Wnt/β-catenin pathway may have important clinical therapeutic value in gastric cancer." (PMID 38952556, 2024). "In gastric cancer, SNX5 prevents the internalization of LRP5 and enhances its recycling back to the cell membrane, thereby averting its degradation in the lysosome." (PMID 40940800, 2025). "In gastric cancer tissue, elevated levels of Wnt proteins, FZD7 receptor, and LRP5/6, along with β-catenin accumulation and reduced APC expression, are associated with poor prognosis." (PMID 40943055, 2025). "Previous studies have demonstrated that Hsp90ab1 binds LRP5 to activate AKT and Wnt/β-catenin signaling, promoting invasion and metastasis in gastric cancer cells." (PMID 40713830, 2025). "Hsp90ab1, an isoform of heat shock protein 90, inhibits ubiquitin-mediated degradation of LRP5, leading to the upregulation of multiple targets of Wnt/β-catenin, activation of the Wnt pathway, and promotion of the EMT in gastric cancer cells." (PMID 38952556, 2024).